KRT18 (keratin 18)
Diseases named in the same sentence as KRT18 in open-access papers (continued):
Sharing a sentence is not in itself a finding about the gene and the disease.
hepatocellular carcinoma (24 papers, 2009 to 2025). A malignant tumor that arises from hepatocytes. "Plectin deficiency in hepatocellular carcinoma results in abnormal expression of cytokeratin 18 and disassembled hemidesmosome." (PMID 25774093, 2015). "In hepatocellular carcinoma, KRT18 deficiency accelerated liver tumor development." (PMID 31345960, 2019). "However, conflicting reports have implicated KRT18 expression in carcinogenesis metastatic hepatocellular carcinoma (HCC) tissue and as a predictive marker for lymph node metastasis in esophageal squamous cell cancer." (PMID 19216797, 2009). "It has also been previously reported that KRT18 interacts with several structural proteins in hepatocellular carcinoma including plectin, which is a multifunctional cytoplasmic cross-linked protein with multiple binding sites for cytoskeletal components." (PMID 40475465, 2025). "In hepatocellular carcinoma, the deletion of keratin 8 and keratin 18 promotes the proliferation, invasion, and metastasis of HepG2 cells by upregulating claudin 1 expression." (PMID 35789645, 2022). "In hepatocellular carcinoma patients, KRT18 overexpression served as an unfavorable prognostic predictor for 1-year survival." (PMID 31345960, 2019). "In hepatocellular carcinoma patients, levels of KRT18 expression were positively correlated with lymph node metastasis and aggressive phenotype." (PMID 31345960, 2019). "Studies showed elevated circulating caspase-cleaved cytokeratin 18 in colorectal cancer with liver metastases and hepatocellular carcinoma (HCC) patients." (PMID 37510802, 2023). "Thus, the role of KRT18 in hepatocellular carcinoma requires further study." (PMID 32509787, 2020). "Cytokeratin 18 (CK18) is upregulated in many types of human cancers (e.g., hepatocellular carcinoma, cervical carcinoma) and is correlated with clinical progression and worse prognoses." (PMID 35055034, 2022).
lung cancer (24 papers, 2008 to 2025). A malignant neoplasm involving the lung. "And the diminished KRT18 expression was reported to improve the susceptibility of cytokine-induced death of cervical cancer cells and inhibit cell migration and enhance paclitaxel sensitivity in lung cancer cells." (PMID 34290732, 2021). "After correcting for multiple testing (0.05/533 exGS tests), we identified 28 associations, including 24 for NHL, 2 for leukaemia (SRP14, TREML2), 1 for both liver (KRT18) and lung cancer (TNR)." (PMID 38750076, 2024). "KRT18 knockdown reduced cell migration and promoted paclitaxel-induced apoptosis in lung cancer cells." (PMID 38817872, 2024). "In lung cancer patients, KRT18 expression was suggested to be correlated with clinical lymph node metastasis." (PMID 31345960, 2019). "KRT18 shows a higher expression level in group 1 of lung cancer samples than in group 2 of lung cancer samples and in normal samples." (PMID 31856825, 2019). "In a similar way, KRT18_SCUBE3 and KRT18_RBM5 were found as potential prognostic gene pairs for lung cancer." (PMID 31856825, 2019). "A transient knockdown of KRT18 decreases cell migration in lung cancer cells." (PMID 35745691, 2022). "In addition, KRT18 expression had 4.6-times increase in high metastatic lung cancer cell line compared with low metastatic lung cancer cell line." (PMID 31345960, 2019). "Among these proteins, we selected seven candidates (PC, keratin 18, heat shock 70 kDa protein-8, lectin galactoside-binding soluble 3 binding protein, DNA-dependent protein kinase catalytic subunit, plakophilin-3, cortactin) that have been known to participate in lung cancer progression." (PMID 34249688, 2021). "The strongest association was for SRP14 with leukaemia [1.22 (1.16–1.28)] followed by KRT18 for liver cancer [1.29 (1.18–1.42)], CD1C for NHL [1.11 (1.06–1.16)] and TNR for lung cancer [0.92 (0.89–0.95)." (PMID 38750076, 2024). "CK18-Asp396 (M30 antigen) is a caspase-degraded product of cytokeratin 18 (CK18), produced by apoptotic epithelial cells, and is elevated in breast and lung cancer patients." (PMID 19302716, 2009). "Some of these genes have been well characterized in lung cancer, for instance, NAPSA29 is a common prognostic marker for LUAD, and KRT18, KRT7, and GPRC5A have been reported to play important roles in tumor progression and chemoresistance in various types of cancers." (PMID 35102706, 2022).
breast tumor (22 papers, 2009 to 2025). "We first determined mRNA levels of NME4 (encoding NDPK-D), CDH1, and KRT18 (encoding the two well-known epithelial markers E-cadherin and cytokeratin 18, respectively), in an important cohort of 526 human breast tumors from patients with well-documented follow-up by using RT-qPCR." (PMID 34674701, 2021). "Breast tumor cells are known to express cytokeratin 18 at the high level." (PMID 25329802, 2014). "Epithelial markers, cytokeratin 18, in particular, were found to be reduced in BCRP overexpressing chemotherapy‐resistant breast tumor tissues." (PMID 40654246, 2025). "The METABRIC database (1904 human breast tumors) consistently revealed a positive association of NME4 with epithelial markers CDH1 and KRT18 and a negative association with mesenchymal markers CDH2 and VIM as well as many EMT drivers like ZEB1, ZEB2, SNAI2, TWIST1, and TWIST2." (PMID 34674701, 2021).
colon carcinoma (20 papers, 2005 to 2024). "In colon cancer the standard for IHC is to detect the presence of aberrant cytokeratin 20 staining in lymph nodes, while in renal cancer cytokeratin 18 is used to demonstrate metastasis." (PMID 30290760, 2018). "This approach lead to the identification of 20 agents that induced strong increases in the levels of caspase-cleaved cytokeratin 18 in colon carcinoma cells." (PMID 19798419, 2009). "The promoter of the keratin 18 gene is deregulated in cells of the human colon carcinoma cell line SW613-S by an unusual mechanism that is acting on the minimal promoter and involves alteration of an acetylation mechanism acting on a non-histone substrate." (PMID 15831101, 2005). "Moreover, HM of colon, colon cancer tissues and cell cultures expressed cytokeratin 18, whereas only healthy and cancer mucosa expressed cytokeratin 20, when analyzed by RT-PCR." (PMID 25738332, 2015). "KRT18 was previously identified as being upregulated in colon carcinoma cells." (PMID 23865481, 2013). "Cytokeratin 18 increases have also been reported in response to doxorubicin treatment of FaDu head and neck carcinoma xenografts, and following treatment of SW620 colon carcinoma xenografts with the Aurora kinase inhibitor AZD1152." (PMID 22033270, 2011). "For colon cancer, the tag AGGACCATCG, belonged to the keratin 18 (KRT18) gene, is reported to be overexpressed in SW613-S human colon carcinoma cell line, compared to nontumorigenic control." (PMID 21179408, 2010). "For exploring the expression pattern of KRT18 in CRC, we first observed KRT18 expression in TCGA and GTEx databases, and found levels of KRT18 expression were dramatically increased in colon cancer and rectal cancer tissues compared with corresponding normal tissues (both P<0.001)." (PMID 31345960, 2019). "The promoter of the keratin 18 (K18) gene is 5- to 10-fold more active in tumorigenic (T-type) cell clones derived from the SW613-S human colon carcinoma cell line than in non-tumorigenic (NT-type) clones." (PMID 15831101, 2005).
pancreatic cancer (20 papers, 2010 to 2025). "While some associate KRT18 with a shorter overall survival of pancreatic cancer patients, others have implicated low KRT18 expression with a more aggressive pancreatic cancer phenotype." (PMID 41209344, 2025). "For pancreatic cancer, the effect of KRT18 dysregulation has been controversially discussed in the literature." (PMID 41209344, 2025). "As expected, all three subtypes of cancer cells expressed the generic pancreatic cancer cell marker genes, such as Krt8 and Krt18." (PMID 37998349, 2023). "All these three cancer cell subtypes expressed the generic pancreatic cancer cell marker genes, such as Krt8 and Krt18." (PMID 37190324, 2023). "In summary, our single-cell RNA sequencing and bioinformatics analysis identified several highly variable genes including IFI27, KRT18, KRT19, MMP1, MMP3, and NEFL, whose expression is associated with a shorter overall survival of pancreatic cancer patients." (PMID 36010660, 2022). "Therefore, further research regarding the role of KRT18 and the other cytokeratins in pancreatic cancer, preferably in 3D models, could be of great interest." (PMID 41209344, 2025). "GW also leads to the phosphorylation of keratin 18 (KRT18), contributing to cytoskeletal reorganization during cell death, underscoring CB2R activation as a potential therapy for pancreatic cancer." (PMID 40483537, 2025). "For instance, in pancreatic tumors, the expression of SOX9 positively correlates with the expression of epithelial phenotype genes (CDH1, KRT7, KRT18, and KRT19) and negatively correlates with the expression of the mesenchymal phenotype gene VIM." (PMID 35884771, 2022). "Reliable markers of PACC have been slowly emerging such as carcinoembryonic antigen (CEA), cytokeratin 18 (CK18) and B-cell lymphoma/leukemia 10 (BCL10) allowing us to distinguish acinar cell carcinoma from normal acinar cells or other pancreatic cancers through histology." (PMID 27165126, 2016). "As expected, epithelial markers (Krt7, Krt8, Krt18, Krt19, Epcam, Egfr, Cdh1) were highly expressed in primary pancreatic tumors and in the cancer cell line NB508 and nearly absent in the nonepithelial MEFs and in normal WBCs." (PMID 25242334, 2014). "However, the exocrine (amylase) and the ductal (krt18) marker were highly expressed in the control but not in the KRASG12D-induced pancreatic tumors." (PMID 31231585, 2019).
Cirrhosis (19 papers, 2010 to 2025). A chronic disorder of the liver in which liver tissue becomes scarred and is partially replaced by regenerative nodules and fibrotic tissue resulting in loss of liver function. "In addition, cytokeratin 18 is also associated with apoptosis of liver cells in cirrhosis." (PMID 31052333, 2019). "In patients with cirrhosis, plasma Hep-EVs contained high levels of cytokeratin-18 compared with healthy individuals." (PMID 32850903, 2020). "We further demonstrate that this was achieved by using two different markers, ASGPR and HepPar1 instead of previously demonstrated cytokeratin 18, which is only detectable at late stages of cirrhosis." (PMID 31052333, 2019). "Recently, hepatic microvesicles were shown to predict mortality in patients with cirrhosis using cytokeratin 18 as a marker for hepatic vesicles." (PMID 31052333, 2019). "These cytokeratin 18 positive vesicles are however only detectable in patients with cirrhosis and were measured by an ELISA based assay." (PMID 31052333, 2019). "Alcohol- or HCV-induced cirrhosis has been shown to have elevated levels of leuko-endothelial (CD31+/41−), lymphocyte (CD4+), pan-leukocyte (CD11a+), erythrocyte (CD235a+), and cytokeratin-18 (CK18) positive micro-vesicles." (PMID 37759769, 2023).
colorectal cancer (19 papers, 2009 to 2025). A primary or metastatic malignant neoplasm that affects the colon or rectum. "KRT18 was found to be over expressed in many different types of cancer including that of colorectal cancer and associated with tumor stage, cancer migration, and invasion." (PMID 32509787, 2020). "KRT18, which has been reported to promote migration and invasion in gastric and colorectal cancer, was also highly expressed." (PMID 39949777, 2025). "Of note, Krt18 is correlated with the malignant status and acts as an oncogene in colorectal cancer as for FAT2, an independent prognostic factor for the poor prognosis of gastric carcinoma." (PMID 35572581, 2022). "KRT18 is a known triple negative breast cancer marker and has also been reported to play a role as oncogene in colorectal cancer." (PMID 32731431, 2020). "Such an increase of keratin 18 has been shown previously in colorectal carcinomas." (PMID 36979679, 2023). "Studies have also shown that KRT18 plays a pivotal role in colorectal cancer progression, suggesting that the protein may be a therapeutic target for improving the prognosis of patients with colorectal cancer." (PMID 36046345, 2022). "However, highly expressed KRT15 protein may contribute to esophageal carcinoma progression, whereas overexpression of KRT18 in colorectal cancer exerts an oncogenic role." (PMID 35328735, 2022). "Keratin 18 (KRT18) has been suggested to be overexpressed in most types of human tumor, but the expression pattern of KRT18 in colorectal cancer (CRC) remained unknown." (PMID 31345960, 2019).
Insulin resistance (19 papers, 2014 to 2026). Increased resistance towards insulin, that is, diminished effectiveness of insulin in reducing blood glucose levels. "The aim of the study was to analyze the associations of cytokeratin-18 with not only fatty liver markers but also obesity-related metabolic disturbances, including insulin resistance, impaired lipid metabolism and the secretion of hepatokines, adipokines and pro-inflammatory cytokines." (PMID 37189422, 2023). "For instance, the understanding of the role played by hepatocyte apoptosis and insulin resistance in the pathobiology of liver injury has enabled the development of promising biomarkers of NASH, such as caspase-cleaved cytokeratin 18 fragments or numerous different adipokines." (PMID 26844476, 2016).
squamous cell carcinoma (19 papers, 2008 to 2025). A carcinoma arising from squamous epithelial cells. "Aberrant expression of KRT8 and KRT18 is associated with neoplastic progression and invasion in squamous cell carcinomas." (PMID 27711225, 2016). "For example, abnormal expression of KRT8 and KRT18 is related to tumor progression and invasion in squamous carcinomas." (PMID 36610719, 2023). "Cytokeratin 18 is primarily used as a positive marker for monolayer epithelia and is a negative marker in compound squamous epithelia, and therefore is often used in the differential diagnosis of squamous cell carcinoma and adenocarcinoma." (PMID 40144068, 2025). "In contrast, only three genes (KRT8, KRT18, and GAPDH) correlate with significantly reduced OS of squamous cell carcinoma patients (N = 525), mirroring the histological classification of the murine KM tumours as adenocarcinoma." (PMID 31032816, 2019). "With regards to routine histopathological workup, we identified KRT18 in combination with UCHL1 as potential immunohistochemical markers to differentiate NEC-like IDH2 and NEC-like SMARCA4/ARID1A tumors from adenoid cystic carcinomas, olfactory neuroblastomas and squamous cell carcinomas." (PMID 36443295, 2022).
gastric cancer (18 papers, 2003 to 2024). A primary or metastatic malignant neoplasm involving the stomach. "In gastric cancer, high KRT18 expression was suggested to be associated with positive lymph nodes, advanced clinical stage, and chemoresistance." (PMID 31345960, 2019). "A similar regulatory mechanism has been reported for another potential RBP, KRT18, in gastric cancer." (PMID 37547464, 2023). "Works found that KRT18 facilitated the progression of gastric cancer and is relating to the prognosis of GC patients." (PMID 36213576, 2022). "To investigate the connection between KRT18 and gastric carcinoma, we analyzed KRT18 expression pattern of STAD samples from The Cancer Genome Atlas (TCGA) database, including 415 tumor tissue and 35 normal (para-carcinoma tissue) samples." (PMID 34290732, 2021). "Krt18 regulates the alternative splicing of genes involved in the proliferation of gastric cancer." (PMID 35252219, 2021). "Keratin 18 (KRT18), one of the most abundant keratins in epithelial and endothelial cells, has been reported to be aberrantly expressed in many malignancies and extensively regarded as a biomarker and important regulator in multiple cancers, including gastric cancer (GC)." (PMID 34290732, 2021). "KRT18 could induce proliferation, migration, and invasion via MAKP signaling in gastric cancer." (PMID 34447748, 2021).
Obesity (18 papers, 2015 to 2025). Accumulation of substantial excess body fat. "KRT18 and some other keratin genes have also been identified to be associated with obesity-caused fatty liver." (PMID 26672748, 2015). "The anthropometric measures, obesity-related biochemical results, and levels of tumor necrosis factor-α, interleukin-6, caspase-cleaved cytokeratin fragment of cytokeratin 18 (M30), and adiponectin were also checked." (PMID 30671426, 2018). "This biomarker panel is used to diagnose obesity-related NASH based on adiponectin, cleaved cytokeratin 18 (CK-18) M30, and resistin levels." (PMID 35096868, 2021).